TBL2 (transducin beta like 2)
Synonyms: WS-betaTRP; WBSCR13; DKFZP43N024
Tractability: PROTAC: UniProt records ubiquitination sites on it; ubiquitination databases record sites on it; its protein half-life has been measured.
Gene: Protein-coding gene on chromosome 7 (73,567,537 to 73,578,791, reverse strand). Ensembl gene ENSG00000106638.
Subcellular location (Human Protein Atlas): Cytosol
Gene Ontology:
Molecular function: phosphoprotein binding; protein binding; protein kinase binding; RNA binding; translation initiation factor binding
Biological process: cellular response to glucose starvation; cellular response to hypoxia; endoplasmic reticulum unfolded protein response
Cellular component: cytosol; endoplasmic reticulum; endoplasmic reticulum membrane
Genetic constraint (gnomAD): Loss-of-function variants: 33 observed, 41.86 expected, observed/expected ratio (o/e) 0.79, 90% interval 0.6 to 1.05. The upper end of that interval is the gene's LOEUF score, 1.05, which puts it in group 4 of 6, group 1 being the genes least tolerant of losing a copy. Missense variants: 522 observed, 610.36 expected, observed/expected ratio (o/e) 0.86, 90% interval 0.8 to 0.92. Synonymous variants: 239 observed, 239.98 expected, observed/expected ratio (o/e) 1, 90% interval 0.89 to 1.11.
Homologues: Orthologues: chimpanzee TBL2 (99% identical), macaque TBL2 (97% identical), pig TBL2 (89% identical), rabbit TBL2 (89% identical), rat Tbl2 (88% identical), mouse Tbl2 (87% identical), guinea pig TBL2 (84% identical), tropical clawed frog tbl2 (65% identical), zebrafish tbl2 (61% identical). Paralogues in human: MAPKBP1 (18% identical), AHI1 (16% identical), TEP1 (16% identical), WDR62 (16% identical), WDR27 (16% identical), POC1A (15% identical), POC1B (15% identical), WDR17 (15% identical), WDR7 (15% identical), WDR75 (15% identical), WDR43 (14% identical), SNRNP40 (14% identical), and 14 more.
Diseases named in the same sentence as TBL2 in open-access papers:
TBL2 is named in the same sentence as 18 diseases in open-access papers, as found by Europe PMC text mining. Sharing a sentence is not in itself a finding about the gene and the disease. The quoted sentences say what the papers report.
dyslipidemia (2 papers, 2022 to 2024). "The DNA methylation level of the TBL2 gene was lower in the dyslipidemia group than in the control group consistent with previous findings." (PMID 36570009, 2022).
Williams-Beuren syndrome (2 papers, 2014 to 2015). "TBL2 has been associated with some disorders like Williams-Beuren syndrome (WBS), in which the TBL2 gene is typically deleted." (PMID 25393282, 2014). "Such functions are also known for the genes that are ECpiC loci, such as the oncogenic transcription factors ABL2 and ELK4, the miRNA effector AGO2, and TBL2 and KCTD7 genes that are in the deleted locus of Williams-Beuren syndrome patients, which display developmental defects." (PMID 26588211, 2015).
breast carcinoma (1 paper, 2024). "We examined the role of TBL2 in the progression of breast cancer through gain or loss‐of‐function methods." (PMID 39499734, 2024). "We first examined the expression of TBL2 in human breast cancer tissues using the Cancer Genome Atlas dataset (TCGA), which revealed an upregulation compared to normal breast tissues." (PMID 39499734, 2024). "By elucidating the precise domains involved, we can further explore the functional implications of TBL2's regulatory role in breast cancer progression." (PMID 39499734, 2024). "Through comprehensive analysis of patient samples, the study reveals TBL2's selective overexpression in breast cancer, correlating with poor prognosis." (PMID 39499734, 2024). "This highlights TBL2 as a promising therapeutic target for breast cancer treatment." (PMID 39499734, 2024). "Moreover, when we exposed TBL2‐deficient MDA‐MB‐231 cells to the AKT‐specific activator SC79, we observed that activated AKT was able to restore the proliferation capacity of these cells, providing further evidence that TBL2 impacts breast cancer cell proliferation via the AKT pathway." (PMID 39499734, 2024). "Mechanistically, TBL2 acts as a scaffold protein enhancing PRMT5‐WDR77 interaction, leading to increased AKT activation and breast cancer proliferation." (PMID 39499734, 2024).
breast tumors (1 paper, 2025). "In certain cases, targeting direct activators such as TBL2 and PRMT5 has been explored as a potential therapeutic strategy for breast tumors, or even the complete inhibition of EGFR/PI3K/AKT and mTOR mediated pathways using natural compounds." (PMID 39950162, 2025).
coronary artery disease (1 paper, 2020). "In a previous study, the TBL2 gene was identified as a genetic locus affecting lipid concentration, which can lead to hypertriglyceridemia and increase the risk of coronary artery disease." (PMID 32811528, 2020).
hypertriglyceridemia (1 paper, 2020). A laboratory test result indicating elevated triglyceride concentration in the blood. "In a previous study, the transducin (β)-like 2 (TBL2) gene was identified as a new genetic locus affecting lipid concentration, which can lead to hypertriglyceridemia disease." (PMID 32811528, 2020).
lipidemia (1 paper, 2014). "In addition to genetic loss of TBL2, SNP in the human TBL2 gene has been reported to associate with increased blood triglycerides, a lipidemia marker, although the effect of SNP on TBL2 function is unknown." (PMID 25393282, 2014).
retinitis pigmentosa (1 paper, 2021). Retinitis pigmentosa (RP) is an inherited retinal dystrophy leading to progressive loss of the photoreceptors and retinal pigment epithelium and resulting in blindness usually after several decades. "Strikingly, eight of the 67 exclusive candidates are associated with retinitis pigmentosa (human orthologues in parentheses): Gnat1 (GNAT1), Rom1a and Rom1b (ROM1), Kfharr-r2 (SAG, ARRESTIN, RP47), Rgra (RGR, RP44), Tbl2 (TBL2), Sec31b (SEC31B) and Glyr1 (GLYR1)." (PMID 34106226, 2021).
Schnyder corneal dystrophy (1 paper, 2013). Schnyder corneal dystrophy (SCD) is a rare form of stromal corneal dystrophy characterized by corneal clouding or crystals within the corneal stroma, and a progressive decrease in visual acuity. "Remarkably, germline mutations in TERE1 cause a rare disease of elevated corneal cholesterol and lipid deposition called Schnyder's Corneal Dystrophy, SCD, and these mutations alter binding to APOE, HMGR, and TBL2." (PMID 23919967, 2013).
tumor (3 papers, 2014 to 2024). "We also examined the role of TBL2 under low glucose and hypoxic conditions, which arephysiological cell conditions observed in the tumor microenvironment or during ischemia and that cause the UPR." (PMID 25393282, 2014). "To validate these observations, we conducted real‐time PCR and western blotting analyses, which consistently exhibited a significant increase in TBL2 expression in both BC tumor tissues and cell lines." (PMID 39499734, 2024). "Weekly BLI TBL2 Acts as a Scaffold to Promote the Interaction Between PRMT5 and WDR77(Bioluminescence imaging) showed higher tumor loads in the TBL2‐overexpression group and lower tumor loads in the TBL2‐silenced group." (PMID 39499734, 2024). "Tumor growth was significantly accelerated in the TBL2‐overexpressing group and suppressed in the TBL2‐silenced group." (PMID 39499734, 2024). "The tumor‐promoting effects of TBL2 on cell proliferation were further verified in in vivo studies using orthotopic mouse models of BC." (PMID 39499734, 2024). "These phenotypic similarities may imply that TBL2 is involved in tumor cell adaptation to poor nutrient conditions through induction of ATF4." (PMID 25393282, 2014).
infection (1 paper, 2023). The state of being infected such as from the introduction of a foreign agent such as serum, vaccine, antigenic substance or organism. "We found that GAS5 and TBL2 were significantly upregulated, respectively, at 9 and 3 h post-infection compared to the previous time points." (PMID 36768954, 2023). "In this light, increased GAS5, TBL2, ATF4, and DDIT3 would be explained as related to cell stress upon infection." (PMID 36768954, 2023). "Known NMD substrates related to cell stress (Growth Arrest Specific 5, GAS5; transducin beta-like 2, TBL2; and DNA damage-inducible transcript 3, DDIT3) were increased in infected cells, possibly as a result of alterations in the NMD pathway and of a direct effect of the infection." (PMID 36768954, 2023).
TBL2 also shares sentences with these, for which no sentence is quoted: cancer (2 papers); bladder cancer (1); glioma (1); lung adenocarcinoma (1); ovarian carcinoma (1); Sepsis (1); Stroke (1).